WWP2 (WW domain containing E3 ubiquitin protein ligase 2)
Description:
E3 ubiquitin-protein ligase which accepts ubiquitin from an E2 ubiquitin-conjugating enzyme in the form of a thioester and then directly transfers the ubiquitin to targeted substrates. Polyubiquitinates POU5F1 by 'Lys-63'-linked conjugation and promotes it to proteasomal degradation; in embryonic stem cells (ESCs) the ubiquitination is proposed to regulate POU5F1 protein level. Ubiquitinates EGR2 and promotes it to proteasomal degradation; in T-cells the ubiquitination inhibits activation-induced cell death. Ubiquitinates SLC11A2; the ubiquitination is enhanced by presence of NDFIP1 and NDFIP2. Ubiquitinates RPB1 and promotes it to proteasomal degradation.
Synonyms: AIP2; WWp2-like
Tractability: Small molecule: a structure with a bound ligand is known. PROTAC: UniProt records ubiquitination sites on it; ubiquitination databases record sites on it; its protein half-life has been measured.
Gene: Protein-coding gene on chromosome 16 (69,762,281 to 69,944,553, forward strand). Ensembl gene ENSG00000198373.
Subcellular location: Nucleus
Pathways (Reactome):
Signal Transduction: NOTCH3 Activation and Transmission of Signal to the Nucleus; RHOJ GTPase cycle; RHOQ GTPase cycle; RHOU GTPase cycle; Regulation of PTEN stability and activity
Gene Ontology:
Molecular function: potassium channel inhibitor activity; protein binding; RNA polymerase II-specific DNA-binding transcription factor binding; transmembrane transporter binding; ubiquitin protein ligase activity; ubiquitin-protein transferase activity; transcription regulator inhibitor activity; molecular function inhibitor activity
Biological process: extracellular transport; negative regulation of potassium ion export across plasma membrane; negative regulation of transcription by RNA polymerase II; proteasome-mediated ubiquitin-dependent protein catabolic process; protein autoubiquitination; protein ubiquitination; regulation of membrane potential; negative regulation of DNA-templated transcription; negative regulation of Notch signaling pathway; protein K63-linked ubiquitination; regulation of monoatomic ion transmembrane transport; symbiont entry into host cell; ubiquitin-dependent protein catabolic process
Cellular component: extracellular exosome; membrane; nucleus; cytoplasm; cytosol; ubiquitin ligase complex
Genetic constraint (gnomAD): Loss-of-function variants: 56 observed, 122.39 expected, observed/expected ratio (o/e) 0.46, 90% interval 0.37 to 0.57. The upper end of that interval is the gene's LOEUF score, 0.57, which puts it in group 2 of 6, group 1 being the genes least tolerant of losing a copy. Missense variants: 958 observed, 1,195.5 expected, observed/expected ratio (o/e) 0.8, 90% interval 0.76 to 0.85. Synonymous variants: 447 observed, 460 expected, observed/expected ratio (o/e) 0.97, 90% interval 0.9 to 1.05.
Homologues: Orthologues: chimpanzee WWP2 (99% identical), macaque WWP2 (99% identical), guinea pig WWP2 (96% identical), mouse Wwp2 (96% identical), rat Wwp2 (96% identical), pig WWP2 (96% identical), rabbit WWP2 (95% identical). Paralogues in human: WWP1 (62% identical), ITCH (57% identical), NEDD4L (35% identical), NEDD4 (34% identical), HUWE1 (34% identical), SMURF2 (34% identical), HECW2 (34% identical), SMURF1 (33% identical), HECW1 (33% identical), HACE1 (25% identical), TRIP12 (22% identical), UBE3C (22% identical), and 12 more.
Diseases named in the same sentence as WWP2 in open-access papers:
WWP2 is named in the same sentence as 78 diseases in open-access papers, as found by Europe PMC text mining. Sharing a sentence is not in itself a finding about the gene and the disease. The quoted sentences say what the papers report.
osteoarthritis (9 papers, 2013 to 2024). A noninflammatory degenerative joint disease occurring chiefly in older persons, characterized by degeneration of the articular cartilage, hypertrophy of bone at the margins and changes in the synovial membrane. "This supported earlier reports of allelic expression imbalance of WWP2 in articular cartilage and uncovered the functional molecular mechanism underlying an osteoarthritis effector gene." (PMID 38430365, 2024). "One methylation quantitative trait loci (mQTLs) analysis showed that WWP2 was linked to osteoarthritis genetic risk." (PMID 37359559, 2023). "We identified methylation sites that play a putative causal role in osteoarthritis, for example for the WWP2, BSN, and MFHAS1 genes." (PMID 35679866, 2022). "Using dCas9-DNMT3a to increase DNAm levels at these CpGs in TC28a2 immortalised chondrocytes, effectively recapitulating the observed mQTL effect, resulted in increased expression of full-length and N-terminus WWP2, confirming these isoforms as targets of osteoarthritis risk." (PMID 38430365, 2024). "This functional fine-mapping approach has identified mechanistic links between mQTLs and further confirmed COLGALT2 [37–39TGFB1, RWDD2B and, most recently, WWP2 as osteoarthritis effector genes." (PMID 38430365, 2024). "WWP2 was involved in chondrogenesis and osteoarthritis by regulating cartilage-specific transcription factors." (PMID 37359559, 2023). "Together, these results support a role for genetically determined methylation for WWP2 regulation in osteoarthritis." (PMID 35679866, 2022). "Moreover, the host-miRNA relationship between Wwp2 and miR-140 is evolutionarily conserved among vertebrates and the possibility remains that these two factors cooperate not only in the context of cartilage homeostasis but also pathogenic processes such as osteoarthritis." (PMID 34977596, 2021). "The intronic miR-140, present in the WW domain containing E3 ubiquitin protein ligase 2 (WWP2) gene, decreases the expression of genes that play detrimental roles in osteoarthritis (OA)." (PMID 24257415, 2013). "In a word, WWP2 is involved in modulation of osteoarthritis." (PMID 37359559, 2023). "WWP2 mRNA injection attenuated the severity of osteoarthritis in mouse joints." (PMID 37359559, 2023). "In addition, WWP2 demonstrates decreased expression levels in osteoarthritis-affected articular cartilage derived from samples of affected individuals." (PMID 35679866, 2022). "Interestingly, nuclear factor of activated T cells (NFAT) 3, an NFAT family transcription factor, and TGF-β signaling have been implicated in regulation of miR-140 but not Wwp2 in patients with osteoarthritis." (PMID 32079226, 2020). "In the OA murine model, WWP2 protein levels were significantly down-regulated, and mice lacking the WWP2 gene developed spontaneous osteoarthritis." (PMID 40226783, 2024). "Mice without WWP2 and mice with inactivation type of WWP2 E3 ligase (WWP2-C838A) had spontaneous and induced osteoarthritis." (PMID 37359559, 2023). "Here, we show that mice lacking Wwp2 and mice in which the Wwp2 E3 enzyme is inactivated (Wwp2-C838A) exhibit aggravated spontaneous and surgically induced osteoarthritis (OA)." (PMID 31160553, 2019).
ovarian carcinoma (7 papers, 2014 to 2025). A malignant neoplasm originating from the surface ovarian epithelium. "Mutations removing the Nedd4 family ubiquitin ligase gene WWP2 are commonly found in ovarian cancer and lost WWP2 activity is associated with decreased Notch3 lysosomal degradation and increased signalling activity." (PMID 32210034, 2020). "The overexpression of WWP2 correlates with poor prognosis and proliferation in gastric, liver, lung adenocarcinoma, and ovarian cancers." (PMID 40565600, 2025). "WWP2 functions as an oncogene in liver cancer, breast cancer, endometrial cancer, gastric cancer, lung cancer, oral cancer, and ovarian cancer." (PMID 34458018, 2021). "Taken together, our results provide evidence that WWP2 serves as a tumor suppressor by negatively regulating Notch3 signaling in ovarian cancer." (PMID 25356737, 2014). "If WWP2 is a negative regulator of Notch3, its expression is expected to be down-regulated in ovarian cancer as compared to normal tissues." (PMID 25356737, 2014). "When expression levels of Notch3 was plotted against WWP2 expression levels in ovarian cancer tissues and primary cultures, an inverse correlation in protein expression levels between WWP2 and Notch3 was observed." (PMID 25356737, 2014). "Analysis of The Cancer Genome Atlas dataset showed that the majority of ovarian carcinomas harbored homozygous or heterozygous deletions in WWP2 locus, and there was an inverse correlation in the expression levels between WWP2 and Notch3 in ovarian carcinomas." (PMID 25356737, 2014). "There was a significantly higher Notch3 to WWP2 protein expression ratio than the normal epithelial cells in ovarian cancer tissues, primary cultures of ovarian cancer cells, and ovarian cancer cell lines." (PMID 25356737, 2014). "WWP2 locus was found to be deleted, and its mRNA down-regulated in a significant fraction of ovarian carcinomas." (PMID 25356737, 2014). "Ectopic expression of WWP2 reduced tumorigenicity of ovarian cancer cells, and counteracted Notch3-mediated phenotypes, including promotion of cancer stem-like cell phenotype and platinum resistance, further supporting its tumor suppressor role." (PMID 25356737, 2014). "High expression levels of WWP1 and WWP2 frequently correlate with poor prognosis, increased tumor invasiveness, and reduced survival rates in cancers such as breast, colorectal, lung, liver, and ovarian cancers." (PMID 39949609, 2024). "Over-expression of WWP2 in ovarian cancer cell lines resulted in cell cycle arrest." (PMID 35204725, 2022). "Interestingly, in ovarian high grade serous carcinoma, around 77% of the tumours had deletions of the WWP2 gene, indicating a link between WWP2 down regulation and ovarian cancer." (PMID 35204725, 2022). "In addition to demonstrating WWP2 as a regulator for Notch3 trafficking and signaling activity, this study has established a tumor suppressor role of WWP2 in ovarian cancer." (PMID 25356737, 2014). "In this study, using comprehensive proteome microarray, we have identified WWP2, a NEDD4 family member of E3 ubiquitin ligase, as a negative regulator of Notch3 signaling in ovarian cancer." (PMID 25356737, 2014). "An increase in Notch3 expression level and a decrease in WWP2 level were observed in ovarian cancer cell lines as compared to normal non-transformed epithelial cells." (PMID 25356737, 2014). "Ovarian cancer cells were transfected with empty vector, N3-NEXT, WWP2, or N3-NEXT+WWP2." (PMID 25356737, 2014). "To determine if WWP2 interacted with endogenous Notch3 fragments, we ectopically expressed WWP2-FLAG in OVCAR3 cells because WWP2 expression is relatively low in most tested ovarian cancer cell lines." (PMID 25356737, 2014).
gastric cancer (6 papers, 2021 to 2024). A primary or metastatic malignant neoplasm involving the stomach. "In gastric cancer, elevated expression levels of both WWP1 and WWP2 are significantly associated with worse OS, particularly in early-stage tumors, suggesting a role for these proteins in the early metastatic spread of gastric cancer." (PMID 39949609, 2024). "More interestingly, the in vivo ubiquitination assays revealed that the endogenous ubiquitination of LATS1 protein was markedly suppressed upon WWP2 downregulation in gastric cancer cells." (PMID 36803368, 2023). "Studies show WWP2 also participates in the regulation of the proliferation of malignant tumors such as liver cancer, lung cancer and gastric cancer." (PMID 36257929, 2022). "WWP2 could promote the proliferation of gastric cancer cells in a PTEN-dependent manner, and its silencing will inhibit proliferation and growth of gastric cancer cells, suggesting a vital role of WWP2 in cancer progression." (PMID 35178295, 2022). "Besides, WWP2 silencing enhanced PTEN expression, reducing the growth of gastric cancer cells." (PMID 39166861, 2024).
Hypertension (6 papers, 2020 to 2025). The presence of chronic increased pressure in the systemic arterial system. "We validated a concordant direction of effect sizes of CTBP1, PPM1G, SEPT2, and KRTCAP3 for gout; SKIV2L for heart failure; and AAK1, MAPKAPK5-AS1, POLA2, RSG1, and WWP2 for hypertension." (PMID 38658550, 2024). "Here we focus on WWP2, an E3 ubiquitin ligase that acts as a positive genetic regulator of human and murine cardiac fibrosis, and show that myeloid specific deletion of WWP2 reduces cardiac fibrosis in hypertension-induced NICM." (PMID 36450710, 2022). "Therefore, WWP2‐Septin4 pathway may be a new target for the treatment of atherosclerosis and hypertension." (PMID 32627301, 2020). "This was the first report to confirm WWP2 as the first NEDD4 family member to inhibit endothelial damage and vascular remodeling, providing an insight into IOS-related atherosclerosis and hypertension." (PMID 33110392, 2020). "In in vivo studies using hypertension-induced non-ischemic cardiomyopathy (NICM) mouse models, WWP2 deficiency has reduced cardiac fibrosis and ameliorated disease progression, suggesting that WWP2-mediated IRF7 ubiquitination is a key driver of fibrosis in NICM." (PMID 40362498, 2025).
liver cancer (6 papers, 2021 to 2023). An epithelial or non-epithelial malignant neoplasm that arises from the liver. "For instance, WWP2 is overexpressed in liver cancer, and its overexpression promotes cancer growth and metastasis by regulating the PTEN/Akt pathway." (PMID 36803368, 2023). "Previous studies have indicated that WWP2 is abnormally expressed in a variety of solid tumors, such as lung cancer, glioma and liver cancer." (PMID 36803368, 2023). "Overexpression of WWP2 inhibits the anti-liver cancer effect of doxorubicin through WWP2/AKT/glycolysis axis." (PMID 37582735, 2023). "For example, Ji and colleagues found CPSF7 is activated and regulates liver cancer growth and metastasis by targeting the WWP2/PTEN/AKT signaling pathway." (PMID 33648552, 2021).
Myocardial fibrosis (6 papers, 2019 to 2025). "Myocardial fibrosis is an important therapeutic target in HF cases 113, and WWP2 represents a regulator of TGFβ/SMAD signalling, which has critical functions in the activation and fibrosis of cardiac fibroblasts." (PMID 33110392, 2020). "Therefore, WWP2 plays an important role in controlling pathological myocardial fibrosis and heart failure and improving the clinical prognosis of patients with heart disease." (PMID 32627301, 2020). "This suggests that depletion of the N-terminal part of WWP2 might have a wider role in myocardial fibrosis, preventing the glycolytic metabolic reprogramming required for myofibroblast maturation, and potentially blocking the cell cycle arrest that has been shown to be a feature of fibrosis." (PMID 31399586, 2019). "Several E3 ubiquitin ligases, such as WWP2, SMURF1, and SMURF2, have been identified as key regulators in myocardial fibrosis." (PMID 39055656, 2024). "Nedd4-like E3 ubiquitin-protein ligase WWP2 (WWP2), an E3 ubiquitin-protein ligase of the HTECT-type NEDD4 family, interacts with different substrates to improve diabetes, pathological myocardial fibrosis and heart failure." (PMID 38166045, 2024). "Transgenic mice lacking the N-terminal region of the WWP2 protein show improved cardiac function and reduced myocardial fibrosis in response to pressure overload or myocardial infarction." (PMID 31399586, 2019).
breast carcinoma (5 papers, 2015 to 2025). "Low WWP2 expression is associated with unfavorable overall survival in breast cancer patients." (PMID 40004017, 2025). "Four genes AQP1, LFNG, RASSF2 and WWP2 were reported to be associated with breast cancer." (PMID 31640538, 2019). "Since monomethylated Sox2 interacts with the E3 ligase WWP2 in ESCs, thereby causing its ubiquitination and degradation, we questioned whether the activity of G9a is related to the protein stability of Sox2 in breast cancer." (PMID 26492085, 2015). "Moreover, breast cancer tissues with higher WWP2 expression exhibit decreased Ki67 and NICD1 signals." (PMID 40004017, 2025). "WWP2 expression is downregulated in advanced breast cancer tissues." (PMID 40004017, 2025). "A recent study showed that WWP2 functions as an E3 ligase for the Notch1 intracellular domain (NICD1) at K1821 and acts as a suppressor of breast cancer metastasis." (PMID 40004017, 2025).
glioblastoma (5 papers, 2021 to 2024). The most malignant astrocytic tumor (WHO grade IV). "Interrogation of the TCGA database confirmed that WWP2 is expressed in glioblastoma patient tumors, although at lower levels compared to normal brain." (PMID 34732716, 2021). "TRIM26 interrupts WWP2, a ubiquitin ligase, to prevent SOX2 protein from ubiquitination and degradation in glioblastoma stem cells (GSCs), which maintains the undifferentiated status of GSCs27." (PMID 37604854, 2023). "We then identify WWP2 as a bona fide E3 ubiquitin ligase that targets SOX2 for proteasomal degradation in GSCs in vitro and glioblastoma cells in vivo." (PMID 34732716, 2021). "Since no SOX2-targeting E3 ubiquitin ligase has yet been identified in glioblastoma cells, we tested the role of four E3 ubiquitin ligases (CDH1-APC, CUL4A, UBR5, and WWP2) which have been demonstrated to target SOX2 in other cellular contexts through an RNA interference-based approach in GSCs29–32." (PMID 34732716, 2021). "In glioblastoma, TRIM26 could stabilize SOX2 protein, a pluripotency transcription factor, by inhibiting the interaction of SOX2 with its targeting E3 ubiquitin ligase WWP2 to promote the tumorigenicity of glioblastoma stem cells." (PMID 38773612, 2024). "Quantitative confocal analysis of SOX2 immunofluorescence in WWP2 knockdown tumor cells demonstrated a significant increase in SOX2 intensity in individual cell nuclei compared to control tumor cells, suggesting WWP2 is a SOX2 E3 ligase in glioblastoma cells in vivo." (PMID 34732716, 2021).